ZNF479 (zinc finger protein 479)
Description:
May be involved in transcriptional regulation.
Synonyms: HKr19; KR19
Tractability: PROTAC: ubiquitination databases record sites on it.
Gene: Protein-coding gene on chromosome 7 (57,117,676 to 57,139,864, reverse strand). Ensembl gene ENSG00000185177.
Subcellular location: Nucleus
Pathways (Reactome):
Gene expression (Transcription): Generic Transcription Pathway
Gene Ontology:
Molecular function: protein binding; DNA-binding transcription factor activity, RNA polymerase II-specific; RNA polymerase II cis-regulatory region sequence-specific DNA binding
Biological process: regulation of DNA-templated transcription; regulation of transcription by RNA polymerase II
Cellular component: nucleus
Genetic constraint (gnomAD): Loss-of-function variants: 16 observed, 18.44 expected, observed/expected ratio (o/e) 0.87, 90% interval 0.59 to 1.32. The synonymous counts are far from expectation, so gnomAD's model fits this gene poorly and the ratio says little. Missense variants: 506 observed, 584.56 expected, observed/expected ratio (o/e) 0.87, 90% interval 0.8 to 0.93. Synonymous variants: 145 observed, 200.69 expected, observed/expected ratio (o/e) 0.72, 90% interval 0.63 to 0.83.
Homologues: Paralogues in human: ZNF92 (66% identical), ZNF680 (65% identical), ZNF737 (64% identical), ZNF723 (64% identical), ZNF430 (64% identical), ZNF98 (63% identical), ZNF66 (63% identical), ZNF675 (62% identical), ZNF273 (61% identical), ZNF626 (61% identical), ZNF257 (60% identical), ZNF431 (60% identical), and 6 more.
Diseases named in the same sentence as ZNF479 in open-access papers:
ZNF479 is named in the same sentence as 4 diseases in open-access papers, as found by Europe PMC text mining. Sharing a sentence is not in itself a finding about the gene and the disease. The quoted sentences say what the papers report.
hepatitis B (1 paper, 2019). "Moreover, correlations between the expression of ZNF479 and its downstream factors were more pronounced in HCC patients with hepatitis B. Here, we found that ZNF479 regulates MT-1 expression by modulating ASH2L in HCC." (PMID 31138789, 2019).
cancer (4 papers, 2019 to 2020). A tumor composed of atypical neoplastic, often pleomorphic cells that invade other tissues. "We also found copy number loss of cancer genes such as CCNE1, MAF, MAFB, MYC, ZNF479, and MGMT and copy number gain of FOXA2, CDH10, and GPC5 in at least two WDPM cases." (PMID 32545767, 2020). "Six of these genes have been reported to be associated with cancers, including LOC284933, BOD1L2, MIR7515, ZNF729 and ZNF479, and MKL1." (PMID 32414326, 2020). "Using a set of mutations from 22 cancers we detect 151 putative cancer drivers, of which 79 are not listed in cancer resources and include recently validated cancer associated genes EPHA7, DCC netrin-1 receptor and zinc-finger protein ZNF479." (PMID 30670742, 2019).
tumor (2 papers, 2019). "Of note, ZNF3, ZNF257, ZNF479 and ZNF493, which were found to be mutated in the PanTT26 tumour, also appeared to be mutated in the PanTT39 tumour specimen." (PMID 30377343, 2019). "Because PDTC reduced in vivo tumor growth in nude mice, we examined the expression of ZNF479, MT-1, ASH2L, Menin, DNMT1, and UHRF1 in PDTC-treated tumors from mice." (PMID 31138789, 2019). "siRNA silencing of ZNF479 significantly induced MT-1 expression and attenuated 14-3-3ε-induced cell proliferation and tumor growth." (PMID 31138789, 2019). "Additionally, ZNF479 shRNA significantly reduced tumor size and weight in the in vivo mouse model." (PMID 31138789, 2019). "Further investigation is needed to elucidate the roles of ZNF479 and the MLL complex in HCC tumorigenesis and tumor progression." (PMID 31138789, 2019). "Thus, ZNF479 may play an important role in suppressing MT-1 expression and modulating HCC tumor progression by regulating components of the MLL complex and epigenetic modification." (PMID 31138789, 2019).
ZNF479 also shares sentences with these, for which no sentence is quoted: hepatocellular carcinoma (1 paper).